IL18 (interleukin 18)
Diseases named in the same sentence as IL18 in open-access papers (continued):
Sharing a sentence is not in itself a finding about the gene and the disease.
COVID-19 (continued). "This notion is further reinforced by patient-level data where we observed higher levels of IL-18 in patients who died from COVID-19 compared to survivors." (PMID 36894537, 2023). "Diffuse myocardial macrophages infiltration in the patient biopsy sample suggest an increased level of IL-18 produced by monocytes and macrophages in the heart with COVID-19 vaccine-related myo-pericarditis." (PMID 37112659, 2023). "Taken together, these findings support a novel link between SARS-CoV-2 signaling, mitophagy inhibition, and IL-18 activation, highlighting novel therapeutic targets for major COVID-19 cardiopulmonary complications." (PMID 36894537, 2023). "In agreement with previous studies, we found that severe COVID-19 patients had elevated serum levels of IL-1α, IL-1β IL-6 and IL-18." (PMID 36142255, 2022). "Serum IL-1β and IL-18 levels were also positively correlated with each other in patients with COVID-19 (Spearman’s r = 0.30, p = 0.0028)." (PMID 34997207, 2022). "IL-18 and IL-27, Th1-type cytokines, were highly increased in the patient with COVID-19 vaccine-related myopericarditis compared with vaccinated controls who experienced no cardiac complications." (PMID 35251049, 2022). "In the present study, IL-18 levels were higher in patients who died compared with discharged patients with severe COVID-19." (PMID 36111789, 2022). "Our findings demonstrated that two groups of COVID-19 patients had significant increases in four pro-inflammatory cytokines (IL-1β, IL-6, and IL-18) and two anti-inflammatory cytokines (IL-4 and IL-35)." (PMID 36298501, 2022). "In COVID-19 patients, IL-18 is probably synthetized as part of the cytokine storm, and increased levels were found in non-survivor patients." (PMID 36287942, 2022). "In the endomyocardial biopsy of the patient with myopericarditis after COVID-19 vaccination, we observed diffuse mild infiltration of macrophages and monocytes, which can be a potent IL-18 producer in the heart." (PMID 35251049, 2022). "When stimulated with cytokines IL-12 and IL-18, impaired upregulation of IL-17A, TNFα, granzyme B and perforin was observed in the COVID-19 cohort, and a reduction in perforin was observed." (PMID 34050887, 2022). "In another study that some metabolites like anthranilic acid as effect of other inflammatory cytokine IL-18 led to increase in amino acid in critically COVID-19 patients." (PMID 36381071, 2022). "Actually, an antibody against IL-1R7 has been proposed to reduce inflammatory signalling of IL-18 in COVID-19 patients." (PMID 36238287, 2022). "A characteristic hyperinflammatory state with significantly elevated neutrophil/lymphocyte ratio and ferritin, IL-1Ra, sIL-2rα, and IL-18 levels together with a “low T1 lymphocyte signature” was found in severe/critical COVID-19 patients." (PMID 35425776, 2022). "In contrast to moderate COVID-19 patients, severe COVID-19 patients had higher levels of IL-6, but IL-4, IL-18, and IL-35 between both illness categories were at close levels." (PMID 36675695, 2022). "The receiver operator characteristic (ROC) curve analysis indicated that IL-1β, IL-4, IL-18, and IL-35 were fair (acceptable) predictors for COVID-19 in moderate cases." (PMID 36675695, 2022). "Inflammatory mediators IL-1β and IL-18, the main cytokine products of caspase-1 activation, are observed to be increased in the lungs and sera of patients with symptomatic COVID-19 compared to asymptomatic patients and healthy individuals." (PMID 35265086, 2022). "Previous reports suggest that SARS-CoV-2 infection senses NRLP3 and that increased levels of IL-1β and IL-18 in plasma correlate with disease severity and mortality in patients with COVID-19." (PMID 36498845, 2022). "Once inflammasome complexes are formed, active caspase-1 cleaves and proteolytically activates the proinflammatory IL1-family cytokines, IL-1β and IL-18, typically elevated and characteristic of severe COVID-19 in patients." (PMID 35483404, 2022).
COVID-19 (continued). "Recent evidence proposed that the severity of the coronavirus disease 2019 (COVID-19) in patients is a consequence of cytokine storm, characterized by increased IL-1β, IL-6, IL-18, TNF-α, and IFN-γ." (PMID 36111104, 2022). "Whereas IL-6 was good predictor of COVID-19 in severe cases (AUC > 0.800), IL-18 and IL-35 were fair." (PMID 36675695, 2022). "Among these cytokines, increased interleukin (IL)-18 and IL-6 appear to be the most significant observation, confirming the role of these cytokines in fatal COVID-19." (PMID 35386707, 2022). "We found that Th1-type cytokines IL-18 and IL-27 were increased in the patient with COVID-19 vaccine-related myopericarditis compared to both healthy and vaccine control groups." (PMID 35251049, 2022). "Infected monocytes secrete the pro-inflammatory cytokines interleukin-1β (IL-1β) and IL-18, which contribute to systemic inflammation and severe coronavirus disease 19 (COVID-19)." (PMID 35871170, 2022). "The most important inflammatory mediators released by immune cells during the “cytokine storm” are IFN-α, IFN-γ, IL-1β, IL-6, IL-12, IL-18, IL-33, TNF-a, and TGF-β and they are associated with different clinical features of COVID-19." (PMID 36298472, 2022). "Collectively, these findings suggest that blood monocytes in the patient with COVID-19 vaccine-related myopericarditis are activated to produce IL-18 priming NK cells and T cells." (PMID 35251049, 2022). "Given the elevated IL18 levels in relation to disease severity of COVID-19 patients, we proposed to link IL18 production to immunopathogenic response during SARS-CoV-2 infection." (PMID 36825215, 2022). "We propose IL-18-mediated immune responses and cardiotoxicity as a possible mechanism of myopericarditis following COVID-19 mRNA vaccination." (PMID 35251049, 2022). "IL-6 levels were greater in severe instances compared to moderate COVID-19 patients, but IL-4, IL-18, and IL-35 between both illness categories were at close levels." (PMID 36675695, 2022). "The most relevant results are that resistin, IL-6, IL-8, IL-15, IL-18, MCP-1 and TNF-α are the main cytokines associated to COVID-19 symptomatology; meanwhile resistin, IL-8, IL-15, MCP-1 and TNF-α used to be associated with oxygen therapy necessity." (PMID 35330391, 2022). "Higher levels of IL-1α and IL-18 pro-inflammatory cytokines were also found in fatal COVID-19 serum." (PMID 35386707, 2022). "It has also been reported that serum IL-18 levels on admission are higher in patients with COVID-19 requiring mechanical ventilation and in lethal cases." (PMID 35930243, 2022). "NLRP3 assembly with consequent activation of caspase-1 and downstream consequences like increased active TNF-alpha, IL-1beta and IL-18 are increased in the lungs of fatal COVID-19 cases." (PMID 36555204, 2022). "High plasma levels of IL-18 are seen in our COVID-19 patient cohort and distinguish severely ill from mild disease." (PMID 36275702, 2022). "In the present study, we corroborate in a cohort of COVID-19 patients from the southeast of Spain an elevated concentration of the cytokines IL-6, IL-15, IL-18 and IL-1RA." (PMID 35663992, 2022). "IL-18, a surrogate marker of inflammasome activation, has recently been described as a promising marker of COVID-19 severity." (PMID 35425776, 2022). "We found that serum concentrations of IL-1β (p = 0.0086) and IL-18 (p = 0.0025) were significantly higher in patients with severe COVID-19 as compared with those suffering from mild-to-moderate COVID-19." (PMID 34997207, 2022). "In the patient with myopericarditis following COVID-19 vaccination, we found an increase of monocyte number and IL-18 production." (PMID 35251049, 2022). "Considering that serum and ETA samples of COVID-19 patients were found to have increased levels of IL18, the results obtained by these in vitro experiments highlight crucial therapy applications." (PMID 35159352, 2022).
COVID-19 (continued). "NK cell hyperactivation, likely driven by IL-6, IL6R and IL-18 is a feature of severe COVID-19 as compared to mild or moderate disease." (PMID 36160152, 2022). "Increased inflammasome complex formation in monocytes and increased plasma levels of interleukin-18 (IL-18) was observed in COVID-19 patients with more severe symptoms." (PMID 36009328, 2022). "A candidate COVID-19 therapy is an anti-human IL1R7 antibody that suppresses IL18-mediated inflammatory signaling." (PMID 35145507, 2021). "A phenomenon observed in COVID-19 patients is NLRP3-inflammasome activation leading to the overproduction of IL-18, which is similar to that observed in AOSD." (PMID 34948117, 2021). "sCD25, IL-1Ra, and IL-18 are of special interest as they have rarely been described as prognostic factors in COVID-19." (PMID 34422145, 2021). "High levels of IL18 and the reduction of mucosal-associated invariant T (MAIT) cells have also been identified in COVID-19 and significantly associated with the mortality and poor outcome in SARS-Cov-2 infection." (PMID 33777844, 2021). "Colchicine has been shown to effectively suppress interleukin IL-1b, IL-18 and IL-6 in patients with acute coronary syndrome and is now being trialed in COVID-19 ARDS, albeit it also has very significant side effects." (PMID 33465050, 2021). "Given only established genetic predictors of interleukin-18 exist, we primarily assessed the role of interleukin-18 in COVID-19 by severity, and secondarily the role of interleukin-12, interleukin-23 and IFNγ." (PMID 34911594, 2021). "In conclusion, both active AOSD and severe COVID-19 patients showed elevated Gal-3, Gal-9, and cytokines, including IL-1β, IL-1Ra, IL-10, IL-6, IL-18, and TNF-a, supporting a common link of cytokine storm in the pathogenesis of both diseases." (PMID 34367188, 2021). "In this study, levels of IL-1β, IL-1RA, IL-18, and IL-18BP were higher in patients with COVID-19 than in HVs; however, they were lower than in patients with canonical autoinflammatory diseases." (PMID 33232303, 2021). "The cytokine profiling of COVID-19 patients in our study provided further evidence that the CRS-associated cytokines, such as IL-6, IL-1β, IL-10, IL-18, and IFN-γ, were dramatically elevated in severe patients." (PMID 33712622, 2021). "validated the correlation between increasing cytotoxicity of circulating MAIT cells and severe inflammation response, particularly high levels of IL-18 through analysis data from 102 COVID-19 patients and 80 uninfected controls." (PMID 33777844, 2021). "Active AOSD patients share features of hyperinflammation and cytokine storm with severe COVID-19 patients but possess a distinct cytokine profile, including elevated IL-18, IL-6, IFN-γ, and IL-17A." (PMID 34367188, 2021). "These aggregates are required for caspase-1-mediated IL-1 and IL-18 secretion, highlighting the role of CD14highCD16− monocytes in COVID-19-related inflammation." (PMID 35095880, 2021). "The IL18/IL18R1/HIF-1 signaling axis was found to mediate an increased risk of peripheral vascular disease such as aneurysms and atherosclerosis after COVID-19." (PMID 35069552, 2021). "In our cohort of moderately and severely sick hospitalized COVID-19 patients, IL-6, MIG, TNF-α, IL-8, IL-18 and IP-10 were highest in patients with severe COVID-19." (PMID 34539644, 2021). "Co-staining with CD163 revealed that proinflammatory cytokines IL-1β, IL-6, and IL-18 were more highly expressed in the pulmonary macrophages of COVID-19 patients than in those of control donors." (PMID 34960782, 2021). "We observed higher caspase-1/4/5 activity within the classical monocyte subset from COVID-19 patients when compared to HCs, suggesting this cell subset contributes to IL-1β and IL-18 maturation during COVID-19." (PMID 35095880, 2021). "IFN-α, IFN-β, IFN-λ, and IL-18 were increased in COVID-19 patients when compared to CONTROL subjects." (PMID 34315957, 2021).
COVID-19 (continued). "Serum IL-18 concentration was found to correlate with inflammatory markers and reflect COVID-19 severity, consistent with our findings." (PMID 34489933, 2021). "Analysis based on GSE157859 data set showed that the expression of IL18 was positively correlated with the severity of COVID-19, and the level of IL18 decreased after treatment." (PMID 35069552, 2021). "Univariate analyses were carried out, and 6 cytokines including G-CSF, HGF, IL-10, IL-18, M-CSF and SCGF-β were found to be associated with the severity of COVID-19." (PMID 34489933, 2021). "Blocking IL-18 with recombinant IL18 BP (tadekinig alfa) has therapeutic efficacy for AOSD but has yet to be applied to COVID-19 treatment now." (PMID 34367188, 2021). "Although most of the cytokines examined herein were elevated in both diseases compared with healthy subjects (HC), active AOSD patients had significantly higher levels of IFN-γ, IL-17A, IL-18, and ferritin than COVID-19 patients." (PMID 34367188, 2021). "Recent published studies have reported that elevated inflammatory cytokine (such as TNFα, IL-1β, IL-6, IL-10, IL-17, IL-18, and IFNγ) levels were seen in active COVID-19 cases compared to healthy donors." (PMID 34348897, 2021). "A recent study demonstrated that active caspase-1 (Casp1p20), IL-1β, IL-18, IL-6, and lactate dehydrogenase (LDH) were increased in the serum of patients with COVID-19, and that Casp1p20 and IL-18 are products derived from inflammasomes." (PMID 34025433, 2021). "Both IL-18 and IL-15 were reported as potential factors contributing to respiratory demise in COVID-19 patients." (PMID 34177897, 2021). "It has also been reported that serum IL-18 levels on admission are higher in COVID-19 patients requiring mechanical ventilation and lethal cases." (PMID 33732720, 2021). "For the majority of these cytokines and chemokines, including those that are typically associated with MAS (IL-6, IL-18, IFN-γ, TNF-α, CXCL9) the increase was less pronounced in COVID-19 critical condition than in MAS patients." (PMID 34226537, 2021). "Post-infection driven inflammasome activation in immune cells, epithelial cells and endothelial cells release cytokines, interleukin (IL)-1β and IL-18 which is proportional to the severity of COVID-19 symptoms." (PMID 34276652, 2021). "It is active in patients with COVID-19 and higher levels of IL-18 and Casp1p20 are correlated with COVID-19 severity and poor clinical outcome." (PMID 34485339, 2021). "Patients with COVID-19 show high concentrations of active/cleaved caspase-1 and IL-18 in their sera." (PMID 34360684, 2021). "IL-7 also significantly increased the frequency of IFN-γ expressing cells in COVID-19 patients but to a lower level than that achieved by IL-12/IL-18 stimulation." (PMID 34238985, 2021). "Inflammasomes, are macromolecular inflammatory signalling complexes activated by the detection of pathogenic microorganisms and process pro-inflammatory cytokines (i.e., pro–IL-1β and pro-IL-18) to their bioactive forms, have been investigated in COVID-19." (PMID 33669011, 2021). "Inflammasome-derived products such as Caspase-1 p20 and IL-18 in the sera correlated with the markers of COVID-19 severity, including IL-6 and LDH." (PMID 34960782, 2021). "In summary, several proteins in plasma that are increased in severe COVID-19 patients, such as IL-6, IL-8, IL-18, MCP-1, OPG, and HGF, are more abundant in healthy elderly compared to young individuals." (PMID 34434199, 2021). "Accordingly, we observed higher plasma levels of IL-18 in our cohort of COVID-19 patients when compared to HCs, suggesting systemic inflammasome activation in this group of patients." (PMID 35095880, 2021). "Interleukin-18 was inversely associated with any COVID-19 and very severe COVID-19 using IVW, with a directionally similar estimate for hospitalised COVID-19." (PMID 34911594, 2021).
COVID-19 (continued). "In one clinical study, high activity of caspase-1 was detected in CD3+ CD4+ CD45+ T cells and CD3+ CD45+ T cells, and increased levels of lactate dehydrogenase, a marker of pyroptosis, and IL-18 were observed in COVID-19 patients." (PMID 34360684, 2021). "The comparison of cytokine concentrations in supernatants of PBMCs from COVID-19 patients and healthy subjects indicated that T lymphocytes from COVID-19 patients have lower ability to produce IL-10 and higher ability to produce IL-18 following activation." (PMID 33634100, 2020). "Fold changes of IL-18 were defined as the mean expression level ratio of severe COVID-19 and AOSD to healthy controls." (PMID 33552062, 2020). "Multiple cytokines, including M-CSF (p<0.01), IP-10 (p<0.01), IL-18 (p=0.01) and IL-1RA (p<0.01) were more relevant in predicting COVID Severity Score than more frequently characterized cytokines in the context of COVID-19 such as IL-6 (p<0.01)." (PMID 33269361, 2020). "Fold changes of IL-18 were defined as the mean expression level ratio of severe COVID-19 to healthy controls in the COVID-19 study and active AOSD to healthy controls in our study, individually." (PMID 33552062, 2020). "Our primary goal was to directly compare levels of 6 inflammatory cytokines commonly associated with cytokine storm (IL-1β, IL-1RA, IL-6, IL-8, IL-18, and TNF-α) between severe COVID-19 patients and patients with ARDS or sepsis." (PMID 32706339, 2020). "We measured plasma concentrations of TNF, IL-1β, IL-6, IFN-β, IFN-γ, and IL-18 in a larger cohort of COVID-19 patients." (PMID 32651212, 2020). "Only one investigation reported the exact raw data on IL-18 with healthy control and patients with COVID-19." (PMID 33552062, 2020). "Following PBMC activation with anti-CD3/CD28 antibodies, IL-10 showed lower levels, while IL-18 showed higher levels in supernatants of PBMCs from COVID-19 patients." (PMID 33634100, 2020). "IL-18 has been found overexpressed in symptomatic and severe COVID-19 patients vs. healthy controls." (PMID 33634100, 2020). "Our analysis focused on detecting statistical differences in levels of 6 cytokines associated with cytokine storm (IL-1β, IL-1RA, IL-6, IL-8, IL-18, and TNF-α) between patients with moderate COVID-19, severe COVID-19, and ARDS or sepsis." (PMID 32706339, 2020). "The comparison of cytokine concentrations in supernatants of PBMCs from COVID-19 patients vs. healthy subjects revealed lower concentrations of IL-10 and higher concentrations of IL-18 in supernatants of CD3/CD28-activated PBMCs from COVID-19 patients." (PMID 33634100, 2020). "Regarding the immunohistochemical analysis, there was a statistically significant difference in the expression of the following markers, with higher concentrations in control group B compared to COVID-19 group A: IL-6 (p < 0.0001), IL-18 (p = 0.002), CASP-9 (p < 0.0001), and HIF (p = 0.0327)." (PMID 40004007, 2025). "Considering the great importance of TNF, IL-1β, and IL18 in the pathogenesis of COVID-19, and in order to evaluate whether their levels were lower in mild cases than in severe cases, we analyzed their average expression levels in all groups of patients." (PMID 40141410, 2025). "This pronounced IL-18 elevation aligns with the literature recognizing IL-18 as a critical pro-inflammatory cytokine driving pulmonary inflammation and systemic cytokine storm in severe COVID-19." (PMID 41155286, 2025). "Interestingly, elevated levels of three proteins, namely SLAMF1, IL18 and IL15RA were associated with the risk of developing critical COVID-19 and Long COVID." (PMID 40475767, 2025). "So, if these inflammatory cytokines are critically involved in severe COVID-19, the results from our studies using gene targeted mice indicate a disconnect between the processing and release of IL-1β and IL-18 from inflammasomes, caspases-1/11/12 and pyroptosis." (PMID 40016339, 2025).